IL33 (interleukin 33)
Diseases named in the same sentence as IL33 in open-access papers (continued):
Sharing a sentence is not in itself a finding about the gene and the disease.
liver fibrosis (continued). "In agreement with previous studies, current findings show that IL-33 levels increased significantly in patients with elevated viral loads and liver fibrosis." (PMID 35056005, 2022). "IL-3, IL-17 and IL-33 induce liver fibrosis through various mechanisms, therefore an approach targeting them as a major participant in the “fibrosis pathway” is expected to be worthwhile." (PMID 33841164, 2021). "The expression of type 2 cytokines is reported to promote cholangiocyte proliferation and hepatic fibrosis in BA, and the IL-33–IL-13 axis was correlated with liver fibrosis in patients with BA in our former study." (PMID 34858903, 2021). "IL-33 is an important inflammatory cytokine, which can promote the hepatic fibrosis by mediating a shift to the Th2 paradigm." (PMID 34674752, 2021). "In the “hepatic fibrosis” pathway, eight fibrogenic genes (Pparg, Krt8, H2-Ab1, H2-Aa, Nqo1, Il33, and Ltb) are upregulated, and one gene (Serpina1c) is downregulated." (PMID 33916843, 2021). "For instance, evidence has showed that in acute liver damage, IL-33 can promote tissue-protective activities, while in chronic liver injury, IL-33 promote liver fibrosis." (PMID 34426741, 2021). "In patients with BA, the IL-33/IL-13 pathway was correlated with liver fibrosis progression, in which IL-33 is secreted and binds ST2 receptors on mast cells to release IL-13/TGF-β1, which mediate the process of fibrosis." (PMID 34858903, 2021). "Although the IL-33/IL13 axis clearly promotes liver fibrosis, the specific contribution of ILC2 and type 2 immune cells remains to be investigated." (PMID 33869241, 2021). "IL-33/ST2 pathway is correlated with liver fibrosis progression in BA patients, and mast cells participate in this process." (PMID 35046838, 2021). "IL-33 expression is increased in human fibrotic livers as well as in independent mouse models of liver fibrosis that are based on the administration of the toxins thioacetamide (TAA) or carbon tetrachloride (CCL4)." (PMID 32079296, 2020). "Some reports showed that after egg deposition in the liver, pro-fibrotic factors, such as VEGF, IL-13, TGF-β, or IL-33, also increased and promoted the formation of liver fibrosis." (PMID 33330140, 2020). "In the normal liver, LSEC are the primary source of IL-33, but in liver fibrosis IL-33 is found within activated hepatic stellate cells." (PMID 32106626, 2020). "Therefore, we asked whether IL-33 plays a pathogenic role in liver fibrosis in NIF mice." (PMID 33311540, 2020). "In a murine model of chemical-induced liver fibrosis, the expression of IL-33 was evaluated due to the chronic hepatocellular stress, and then IL-33 mediated the accumulation and activation of ILC2s through ST2-dependent signaling." (PMID 32765518, 2020). "Group 2 innate lymphoid cells are also considered a pro-fibrotic population in the liver and promote liver fibrosis in an IL-33 dependent manner in the CCl4 model." (PMID 33178216, 2020). "In this context, previous reports have shown that the IL-33/ILC2/IL-13 axis exacerbates liver fibrosis in mice, with circumstantial evidence of the activation of this axis in human cirrhosis." (PMID 31022195, 2019). "Hepatic fibrosis occurred in 47.3% (130/275) of our study population independently from plasma levels of IL-33 (AOR 1.00; 95% CI 0.99–1.01)." (PMID 31849991, 2019). "The extent of liver fibrosis coincided with an increase in tTG and IL-33/ST2 expression in the liver of infected mice between five to eight weeks, with a peak of correlation at six weeks after Sj infection." (PMID 31200771, 2019). "IL-33 expression in liver was sufficient for severe hepatic fibrosis in vivo by the activation and expansion of liver-resident innate lymphoid cells (ILC2), which then contribute to fibrosis by producing IL-13." (PMID 31766207, 2019).
liver fibrosis (continued). "We found out that IL-33 expressions in liver and serum are significantly increased in the poor-prognosis BA patients compared to those of the good-prognosis BA group, indicating that IL-33 can be a possible predictor for liver fibrosis stage." (PMID 31632941, 2019). "Since immune dysregulation is a contributor to BA pathogenesis, we aimed to investigate the role of IL-33/ST2 receptor in the progression of liver fibrosis in BA patients." (PMID 31632941, 2019). "As an “alarm” cytokine, IL-33 has been demonstrated to exacerbate inflammatory responses and drive liver fibrosis." (PMID 31632941, 2019). "Herein, the extent of liver fibrosis following Sj infection correlates with the expression level of IL-33 and ST2." (PMID 31200771, 2019). "Given that both IL-33/ST2 and tTG have been implicated in fibrosis through the release of IL-13, this study was undertaken to genetically validate the role of tTG in liver fibrosis during Sj infection and the relationship between tTG and IL-33/ST2." (PMID 31200771, 2019). "This indicates an important role of the IL-33/ST2 receptor signaling axis in the progression of liver fibrosis in BA patients, and provides evidence for the capability of IL-33 being a prognostic biomarker." (PMID 31632941, 2019). "In thioacetamide (TAA) and carbontetrachloride (CCL4) models of hepatic fibrosis, increased IL-33 production favored the expansion and activated liver resident ILC2s." (PMID 31024531, 2019). "The hepatocyte is a major source of IL-33 in mice liver fibrosis models induced by thioacetamide or carbon tetrachloride treatment." (PMID 31200771, 2019). "Treatment with recombinant IL-33 in mice attenuated diet-induced hepatic steatosis but aggravated hepatic fibrosis in a ST2-dependent manner." (PMID 31507607, 2019). "Since it was observed that ECM deposition and thereby fibrogenesis were reduced in mice devoid of either IL-33- or IL-13-signalling, it was concluded that liver fibrosis was solely dependent on activated ILC2s." (PMID 30999584, 2019). "We also explored the difference between subgroups of BA patients with different prognosis, which made it more convincing to elucidate the role of IL-33/ST2 receptor signaling axis in the liver fibrosis progression." (PMID 31632941, 2019). "The IL-33-dependent progression of liver fibrosis was recently demonstrated during chronic liver inflammation in mice." (PMID 30999584, 2019). "Herein, we observed that the extent of liver fibrosis in Sj infection mice is consistent with the expression levels of tTG and IL-33/ST2." (PMID 31200771, 2019). "Remarkably, IL-33 treatment has been proposed to attenuate diet-induced hepatic steatosis on the one hand, but aggravate hepatic fibrosis in an ST2-dependent manner on the other hand." (PMID 30405626, 2018). "Recent studies found a positive correlation between the serum level of IL-33 and the onset of hepatitis B virus- (HBV-) related liver fibrosis, suggesting the possible involvement of IL-33 in the manifestation of chronic hepatitis." (PMID 30034292, 2018). "In contrast, exogenous IL-33 induced opposing effects on disease progression as steatosis was attenuated while hepatic fibrosis was exacerbated." (PMID 30213101, 2018). "Another study deeply explored the mechanism of IL-33 in promoting the pathogenesis of hepatic fibrosis; this mechanism involved a new type of lymphocyte, innate lymphoid cell type 2 (ILC2), which expresses IL33R-ST2." (PMID 29180837, 2017). "One such cytokine is IL-33, which drives bile duct proliferation in children with biliary atresia and is required for the development of hepatic fibrosis in vivo." (PMID 29261670, 2017). "So far, IL-33 has been found to be involved in a variety of liver diseases, including fatty liver disease, hepatitis, liver fibrosis, and cirrhosis, along with other hepatic diseases." (PMID 29180837, 2017).
liver fibrosis (continued). "Based on the crucial role of Th2 cytokines in liver fibrosis formation and the pro-Th2 activity of IL-33, the relationship between IL-33 and liver fibrosis has received much attention." (PMID 29180837, 2017). "In conclusion, treatment with IL-33 attenuated diet-induced hepatic steatosis, but aggravated hepatic fibrosis, in a ST2-dependent manner." (PMID 27172901, 2016). "Computerized image analysis of the slides stained with Mallory-Azan demonstrated that in HFD or MCD-fed mice showed an obvious accumulation of collagens, and treatment with IL-33 aggravated hepatic fibrosis induced by HFD or MCD in mice." (PMID 27172901, 2016). "Hepatic over-expression of IL-33 had been detected in patients with liver fibrosis, chronic hepatitis B and hepatic failure." (PMID 27180842, 2016). "Exogenous IL-33 treatment attenuated diet-induced hepatic steatosis but exacerbated hepatic fibrosis, in a dose-dependent manner." (PMID 27172901, 2016). "In conclusion, IL-33 treatment attenuated both diets-induced hepatic steatosis, but aggravated hepatic fibrosis, in a ST2-dependent manner." (PMID 27172901, 2016). "The importance of IL-33 for liver fibrosis was demonstrated by analyses of several mouse models of liver fibrosis." (PMID 26549942, 2015). "Multiple injections of carbon tetrahydrochloride (CCl4) or thioacetamide, infection with the helminth Schistosoma mansoni, or bile duct ligation induces liver fibrosis in WT mice, accompanied by elevation of serum IL-33 levels." (PMID 26549942, 2015). "St2−/−, Il13−/−, and Il4rα−/− mice are resistant to this treatment, strongly suggesting that the IL-33–IL-13 axis is important for the development of IL-33-induced liver fibrosis." (PMID 26549942, 2015). "Intriguingly, in vivo depletion of ILC2 prevents Rag1−/− mice from developing IL-33-induced liver fibrosis." (PMID 26549942, 2015). "Cytokines involved in liver fibrosis, such as IL-4 or IL-33, act as chemoattractants, driving the activation of mast cells." (PMID 24839609, 2014). "Liver endothelial and hepatic stellate cells (HSCs) constitute the major sources of IL-33 in liver fibrosis, and the increase in IL-33 mRNA levels are likely due to the activation and proliferation of HSCs and/or the increased number of endothelial cells." (PMID 23062310, 2012). "A recent Chinese study reported IL-33 over-expression to be associated with the development and progression of hepatitis C virus (HCV)-related liver fibrosis." (PMID 23423835, 2012). "However, other authors showed that treatment with recombinant IL-33 led to weight loss and improved hepatic steatosis, ALT, and IR in mice fed a HFD, but exacerbated hepatic fibrosis in both HFD and MCD diet NAFLD mice, as shown for IL-17." (PMID 40794228, 2025). "However, while IL-33-targeted therapy mitigates high-fat diet-induced hepatic steatosis, it can exacerbate liver fibrosis through ST2 signaling." (PMID 39995661, 2025). "In a mouse model of hepatic fibrosis, IL-33 knockdown led to a marked improvement in fibrosis." (PMID 39995661, 2025). "Furthermore, it has been supported that IL-33 promotes hepatic fibrosis through the activation and expansion of liver-resident innate lymphoid cells (ILCs), which produce IL-13 that activates HSCs, representing a newly described fibrogenic mechanism." (PMID 40794228, 2025). "Furthermore, in a mouse model of bleomycin-induced pulmonary fibrosis, type 2 cytokines such as IL-13 and IL-33 were reported to promote disease exacerbation, supporting the role of Th2 cells in promoting hepatic fibrosis." (PMID 40616144, 2025). "They show that CCL2, IL-18, and IL-33 are involved in distinct stages of the disease and, particularly, in the onset of the disease, as well as in the hepatic fibrosis that may occur during the chronicity." (PMID 40565198, 2025). "Therefore, the role of IL-33 in promoting liver fibrosis and its elevation in CLD, along with its stimulatory effect on melanin synthesis, is supported by research." (PMID 39689154, 2025).
liver fibrosis (continued). "Since neutrophils are actively infiltrated during the onset of liver fibrosis, secreted IL-33 may be more efficiently converted to its mature form." (PMID 38233853, 2024). "Interleukin-33 (IL-33) expression is upregulated in human and murine hepatic fibrosis." (PMID 36826975, 2023). "However, the role of IL-33 in the activation of HSCs and liver fibrosis induced by the deposition of Schistosoma spp." (PMID 37373379, 2023). "Therefore, the effects of the IL-33/ST2 pathway on hepatic fibrosis and HSC activation and differentiation during S. mansoni infection require further elucidation." (PMID 37373379, 2023). "In both humans and mice with hepatic fibrosis, IL-33 expression is increased." (PMID 35574038, 2022). "However, IL-33 acts as a liver fibrosis factor to aggravate liver deterioration in chronic liver injury." (PMID 35911735, 2022). "Moreover, the IL-33 over expression is correlated to the development of HCV/HBV-induced liver fibrosis." (PMID 35056005, 2022). "Since IL-33 can promote Th2 response and increase the production of type 2 cytokines, such as IL-4, IL-5, and IL-13, which leads to extracellular matrix accumulation, administration of recombinant IL-33 to mice exaggerated liver fibrosis in NASH mice." (PMID 36032141, 2022). "The results indicate a possibility of the use of IL-33 as a biomarker for liver fibrosis progress in patients suffering from CHC, whereas IL-17 and IL-25 could be used as biomarkers for the development of hepatocellular carcinoma." (PMID 35056005, 2022). "In addition, IL-33 serum level was found to increase by liver fibrosis progression and viral load, in contrast to both IL-17 and IL-25." (PMID 35056005, 2022). "The elevated expression of IL-33 is associated with the activation of IL-33 receptor (IL-33R) through ST2 signaling, leading to the increased production of IL-4 and IL-13 with the increase in liver fibrosis." (PMID 36271450, 2022). "The tTG upregulation of IL-33 promotes liver fibrosis and worm egg granuloma." (PMID 36389166, 2022). "Therefore, it is very important to select and study targets capable of blocking pro-inflammatory (IL-13, IL-17, and IL-33) or inducing anti-inflammatory interleukin (IL-10) in the complex process of liver fibrosis." (PMID 33841164, 2021). "Our overall observation of a lack of association between plasma IL-33 and schistosomiasis-driven live disease progression is contrasting with previous reports that have suggested the increase of IL-33 with hepatic fibrosis in general and hepatic schistosomiasis-driven liver fibrosis in particular." (PMID 31849991, 2019). "This pathway results in massive proliferation of the extrahepatic bile duct (EHBD) but also exacerbates liver fibrosis, suggesting that there may be tissue-specific subpopulations of IL-33-induced ILC." (PMID 31022195, 2019). "Moreover, we analyzed the relation between IL-33 expression and Masson score, which presenting the liver fibrosis stage." (PMID 31632941, 2019). "As this in turn, favors release of IL-33, there might be an ongoing activation of ILC2s, which consequently promotes liver fibrosis and cirrhosis and thereby reciprocally impacts the vitality of the gut." (PMID 30999584, 2019). "We found that IL-33 expression is significantly higher in BA patients compared to cholestasis controls and was especially higher in poor prognosis BA patients, indicating that IL-33 is correlated with liver fibrosis progression and can be an indicator for postoperative prognosis." (PMID 31632941, 2019). "IL-33, by inducing IL-13 production in ILC2s, has been shown to have seemingly disparate roles in promoting tissue repair and cholangiocyte proliferation in EHBDs while also exacerbating liver fibrosis." (PMID 31022195, 2019). "A study reported that IL-33 was required and sufficient for severe hepatic fibrosis in vivo." (PMID 31024531, 2019). "IL-33 and ST2 have been reported to be associated with liver fibrosis." (PMID 31200771, 2019).
liver fibrosis (continued). "IL-33/ST2 axis has been implicated in several hepatic diseases, such as cirrhosis, virus infection, fatty liver disease and toxic liver damage leading further to liver fibrosis." (PMID 30405626, 2018). "More contradictory data reported that IL-33 deficiency in mice does not lessen liver fibrosis during diet-induced steatohepatitis." (PMID 30405626, 2018). "In liver fibrosis, evidence indicate that when acute and massive liver damage occurs, the release of IL-33 might act as an activator of tissue-protective mechanisms, while in cases of chronic injury IL-33 plays the role of a hepatic fibrotic factor." (PMID 30405626, 2018). "For instance, melatonin which exerts cytoprotective effects via inhibition of oxidative stress and apoptosis in liver ischemia-reperfusion injury (IRI) has been proposed to inhibit liver fibrosis through suppressing necroptotic DAMPs signaling cascades, such as the IL-33 signaling pathway." (PMID 30405626, 2018). "In conclusion, IL-33 deficiency in mice does not lessen liver fibrosis during diet-induced steatohepatitis, in contrast to previous studies indicating a deleterious role of exogenous IL-33 in chronic liver injury and experimental NAFLD." (PMID 28611297, 2017). "Among all cytokines involved in liver fibrogenesis, we have shown that interleukin (IL)-33 hepatic expression is upregulated in cirrhotic patients and in a toxic model of liver fibrosis, and sustained release of IL-33 from liver cells has been shown to promote severe fibrosis in mice." (PMID 28611297, 2017). "Nevertheless, IL-33 deficiency did not affect the severity of liver inflammation by histological and transcriptomic analyses, nor the quantity of liver fibrosis." (PMID 28611297, 2017). "In conclusion, deficiency of endogenous IL-33 does not affect the evolution of experimental diet-induced steatohepatitis towards liver fibrosis." (PMID 28611297, 2017). "In general, IL-33 showed a potential promotive effect on liver fibrosis." (PMID 29180837, 2017). "Other studies suggested that IL-33 participated in the pathogenic process of acute hepatitis induced by Con-A and IL-33 overexpression was associated with the development of HBV/HCV-related liver fibrosis." (PMID 27180842, 2016). "However, in this work, we found that treatment with IL-33 enhanced hepatic fibrosis in mice fed with HFD." (PMID 27172901, 2016). "Herein, we will focus on the roles of IL-33 in liver fibrosis." (PMID 26549942, 2015). "Intriguingly, multiple introduction of Il33 in the liver of mice induces liver fibrosis." (PMID 26549942, 2015). "Il33−/− mice are resistant to induction of liver fibrosis by these treatments." (PMID 26549942, 2015). "On the other hand, IL-33 has been suggested to play a role in the development of hepatic fibrosis." (PMID 23423835, 2012). "In fact, expression of IL-33 and its receptor/coreceptor, ST2/IL-1RAcP, has been associated with both murine and human liver fibrosis, with a direct correlation between IL-33 and ST2 levels, but not IL-1RAcP, and the severity of fibrosis." (PMID 23062310, 2012). "Recent studies have suggested a possible role for IL-33 in the pathogenesis of liver damage during acute and chronic hepatitis; furthermore, IL-33 may be involved in the development and progression of liver fibrosis." (PMID 23423835, 2012). "However, another study reported that IL-33 deficiency did not attenuate liver fibrosis in a high-fat diet-induced steatohepatitis model." (PMID 39995661, 2025). "In liver fibrosis, IL-33 may play a dual regulatory role through ST2+Treg." (PMID 39995661, 2025). "Notably, one study suggests that inhibiting IL-33 may halt the progression of non-alcoholic fatty liver disease to liver fibrosis and subsequently to hepatocellular carcinoma (HCC), highlighting its potential as a novel therapeutic target." (PMID 39925809, 2025).